SIRT1 (sirtuin 1)
Diseases named in the same sentence as SIRT1 in open-access papers (continued):
Sharing a sentence is not in itself a finding about the gene and the disease.
Obesity (continued). "Therefore, obesity is linked to the disruption of the AMPK/SIRT1 pathway, which potentially plays a vital role in the development of obesity." (PMID 37509819, 2023). "Obesity seems to be associated with a lower SIRT1 activity and increased inflammatory response." (PMID 38304233, 2023). "Therefore, an impaired SIRT1 activity due to NAD + deficiency is implicated in obesity-induced PVAT dysfunction." (PMID 38304233, 2023). "Variations in SIRT1 gene expression levels have been associated with obesity and T2D." (PMID 36747995, 2023). "Histone acetylation was enhanced in children and adolescents with obesity, potentially resulting from down-regulation of SIRT1, and could play a role in the obesity-associated metabolic abnormalities and insulin resistance." (PMID 37862340, 2023). "This aligns with the hypothesis that the reduction of hippocampal SIRT1 due to a HFD may contribute to memory impairment associated with obesity." (PMID 38026693, 2023). "The crosstalk between SIRT1 and autophagy has been implicated in obesity and T2D." (PMID 36747995, 2023). "Genetic variations in SIRT1 gene have been related to the risk for obesity." (PMID 36747995, 2023). "In conclusion, the present study revealed the increased global histone acetylation in children and adolescents with obesity, in line with the downregulation of SIRT1 expression, and a remarkable association between histone hyperacetylation and insulin resistance." (PMID 37862340, 2023). "Therefore, we explored how moderate CR induces weight loss and improves energy metabolism by modulating the AMPK/SIRT1 signaling in a murine model of obesity." (PMID 35721807, 2022). "SIRT1 was associated with obesity-related genes and metabolic disorders." (PMID 36299860, 2022). "Thus, reduced SIRT1 activity due to NAD+ deficiency is involved in obesity-induced PVAT dysfunction." (PMID 35326191, 2022). "Improving SIRT1 activity by elevating NAD+ levels may represent a novel therapeutic strategy for obesity-associated vascular disease." (PMID 35326191, 2022). "SIRT1 levels strongly negatively correlate with the amount of visceral fat B1R in adipocytes regulates glucose tolerance and predisposition to obesity and B1R knockout mice have been shown to be resistant to obesity induced by a high-fat diet." (PMID 39086962, 2022). "One of the possible causes of obesity relates to the following mechanism: The decreased enzymatic activity of SIRTs, particularly SIRT1, due to excessive glycolytic activity, leads to the accumulation of ROS and the subsequent impairment of the physiological antioxidant mechanism." (PMID 35055159, 2022). "SIRT1 dysregulation in hypothalamus and skeletal muscle may also be associated to the development of obesity." (PMID 35909524, 2022). "SIRT1 dysfunction due to NAD+ deficiency is causally involved in obesity-induced PVAT dysfunction." (PMID 35326191, 2022). "There is evidence that in a high-energy state, such as that associated with an HFD and obesity, Sirt1 activity may decline with a decreased level of NAD+." (PMID 35207470, 2022). "Likewise, insulin resistance in skeletal muscles was observed in Sirt1-deficient SF1 neurons, while Sirt1-overexpression resulted in induced obesity and insulin resistance." (PMID 35207605, 2022). "Loss of Sirt1 expression leads to progressive hyperglycemia, obesity, and insulin resistance." (PMID 35435227, 2022). "Moreover, SIRT1 SNPs have been linked with metabolic diseases such as obesity and type 2 diabetes, and animal studies have demonstrated that the SIRT1 protein advances puberty through the regulation of KISS1 expression, which stimulates GnRH secretion." (PMID 36046800, 2022). "Furthermore, sirtuin 1 (SIRT1) produced by visceral WAT is a critical factor in preserving improved glucose tolerance in NRF2 deficiency mice during obesity." (PMID 35204118, 2022).
Obesity (continued). "A moderate maternal energy restriction during gestation could program a certain Sirt1 expression profile in different peripheral tissues in mice, which in turn could be related to obesity predisposition in adulthood." (PMID 34925065, 2021). "Regulation of the genes SIRT1 and klf4 may serve as a mechanism through which miR-34a promotes obesity associated neurodegenerative disorders, implicating its importance as a biomarker." (PMID 34690698, 2021). "In addition, SIRT1 deficiency exacerbates obesity and inflammation in the adipose tissue of obese mice with suppressed AMPK activity." (PMID 34684660, 2021). "SIRT1 alters these macrophages’ recruitment and polarization into adipose tissues by modulating several adipokines’ expression and secretion and decreasing the risk of obesity." (PMID 34746831, 2021). "We confirmed again in the peresent study that the Japanese allele frequencies for SIRT1 rs7895833, which are different from those of Caucasians, might explain why Japanese individuals show less marked obesity than Caucasians." (PMID 33507936, 2021). "AE may activate Sirt-1 expression in obese mice and therefore counter obesity-associated pulmonary fibrosis." (PMID 35115954, 2021). "Expression of SIRT1 stimulates mitochondrial biogenesis, fatty acid oxidation, and ketogenesis, further demonstrating the importance of miR-34a in the regulation of obesity associated metabolic processes." (PMID 34690698, 2021). "Activation or overexpression of Sirt1 improves systemic metabolism and protects against diabetes, obesity, or high-fat diet-induced metabolic damages, while dysregulated Sirt1 resulted in phenotypes associated with diabetes, obesity, and aging." (PMID 33723227, 2021). "Therefore, obesity is associated with dysregulation of the AMPK/SIRT1 pathway, which can be seen to play an important role in the development of obesity." (PMID 32899992, 2020). "Taken together, down-regulation of the SIRT1 may contribute to obesity-associated metabolic abnormalities." (PMID 33324265, 2020). "Sirt1 loss from adipose tissue leads to obesity and metabolic dysfunction." (PMID 32257911, 2019). "Finally, six genes (Sec61a1, Insr, Sirt1, Pdpk1, Sin3a, and Sqstm1) were predicted to be associated with diabetes and obesity." (PMID 32257911, 2019). "Interestingly, SREBP1c mRNA and expression strongly depended on melatonin and SIRT1 in the metabolic syndrome and SIRT1 deficient mice developed sustained hepatic steatosis and obesity." (PMID 31500354, 2019). "Therefore, based on the results of this study, we concluded that CD38 deficiency‐mediated activation of Sirt1 signalling pathway plays a critical role in the development of obesity." (PMID 28816006, 2018). "The decreased expression of SIRT1 is related to obesity and genetic variants located in the SIRT1 gene have been associated with body mass index (BMI) and obesity risk; specifically, a lower BMI has been observed in carriers of the minor alleles of rs7895833 (G) and rs1467568 (A)." (PMID 30518135, 2018). "In addition, we found a polymorphism in the promoter region of SIRT1 gene in obese children drawing attention to the association between altered SIRT1 activity and the risk of obesity." (PMID 30374331, 2018). "However, the mechanism by which Sirt1 activation affects obesity-associated impairments in angiogenesis in the adipose tissue is not fully understood." (PMID 30054532, 2018). "We also evaluated the potential pathophysiological role that SIRT1 may play in eliciting pubertal perturbations associated with early-onset obesity and undernutrition." (PMID 30305620, 2018). "Therefore, the miR-377/SIRT1 pathway is implicated as a potential target for attenuating the inflammatory state in adipocytes during obesity." (PMID 29050301, 2017). "The effects of SIRT1 polymorphisms on susceptibility to DN might be mediated by differences in the metabolic state among individuals, including glycemic control, obesity, blood pressure, respectively." (PMID 28860538, 2017).
Obesity (continued). "It was also shown that some single-nucleotide polymorphisms (SNP) in the SIRT1 gene could affect SIRT1 activity and correlate with BMI and a tendency to diet-induced obesity." (PMID 28258519, 2017). "Interestingly, ω-3 PUFA supplementation has been shown to protect against obesity-associated inflammation and colon carcinogenesis through upregulation of SIRT1." (PMID 28738820, 2017). "Despite the potential importance of SIRT1 in adipogenesis and obesity, the epigenetic mechanism underlying PPARγ repression is largely unknown." (PMID 29233982, 2017). "SIRT1 protects diet-induced obesity and inflammation and obesity-associated metabolic dysfunction." (PMID 28353634, 2017). "An association between the rs12413112 (G/A), rs33957861 (C/T), rs11599176 (A/G) and rs35689145 (G/A) SIRT1 variants, all within high LD and obesity, was confirmed in 896 unrelated French cases and 532 normal-weight controls, and replicated in 154 Swedish families (732 subjects)." (PMID 27104517, 2016). "Thus, obesity is associated with low SIRT1 activity, increased inflammatory response, and expansion of WAT." (PMID 26904696, 2016). "The most studied human isoform is SIRT1, a nuclear protein reported to regulate critical physiological processes and associated with chronic inflammatory diseases and metabolic dysfunctions like diabetes, obesity, aging, and even cancer." (PMID 26788256, 2016). "Pro-inflammatory signaling could underlie the declines in ARC SIRT1 levels during aging and during diet-induced obesity because inflammatory changes occur during aging and during chronic over-nutrition." (PMID 26236282, 2015). "Single nucleotide polymorphisms in human SIRT1 are linked to both adult obesity and childhood obesity, indicating that SIRT1 may regulate body weight." (PMID 26236282, 2015). "If autophagy is inactivated by mTOR activation and AMPK and Sirt1 inactivation in obesity and diabetic renal diseases, autophagy deficiency could enhance organelle dysfunction mediated by nutrient excess, hypoxia, and proteinuria." (PMID 25126552, 2014). "Previous studies showed that some of the SIRT1 SNPs are associated with body mass index and obesity, glucose tolerance and diabetes, blood pressure, cholesterol metabolism and coronary artery calcification which may provide cardiovascular phenotype." (PMID 24587358, 2014). "Genetic variation in SIRT1 is related to BMI and risk of obesity in humans." (PMID 22115311, 2011). "Benefits of SIRT1 over-expression also included less inflammation, better glucose tolerance, and almost complete protection against hepatic steatosis, suggesting that SIRT1 plays an important role in obesity-associated metabolic adverse effects." (PMID 22115311, 2011). "Present research data indicate that Sirt1 plays a vital role in the regulation of hepatic lipid homeostasis and that pharmacological activation of Sirt1 may be important for the prevention of obesity associated metabolic diseases." (PMID 21549004, 2011). "SIRT1 has recently been implicated in the regulation of obesity-related inflammation." (PMID 22115311, 2011). "Sirt1 genetic variation in humans is related to BMI and risk of obesity." (PMID 21426570, 2011). "Furthermore DNMT3a was found to bind to the SIRT1 promoter, suggesting that the RRTFB may regulate SIRT1 methylation by inhibiting DNMT3a activity, thereby mitigating obesity‐associated inflammation and oxidative stress." (PMID 40909259, 2025). "There is strong evidence that Sirt1 regulates glucose and lipid metabolism through its deacetylation activity, and exerts a positive role in ameliorating insulin resistance, which together with obesity is a major cause of endothelial oxidative stress and early vascular aging." (PMID 39273039, 2024).
Obesity (continued). "In order to understand the role that different SIRT1 genetic variants may have in the development and progression of obesity, and its metabolic comorbidities, could be used in conjunction with measuring SIRT1 protein levels as a risk marker and/or diagnosis of these pathologies." (PMID 38645486, 2024). "Thus, interventions stimulating SIRT1 activity could potentially offer therapeutic benefits for the management of hepatic diseases and metabolic syndrome associated with obesity." (PMID 37834101, 2023). "Therefore, CR may promote weight loss and improves obesity-related metabolic indices by activating SIRT1." (PMID 35721807, 2022). "Thus, enhancing SIRT1 activity by improving the NAD+ level may represent a therapeutic strategy for the treatment of obesity-associated vascular complications." (PMID 35326191, 2022). "Furthermore, cellular senescence of AT mesenchymal stem cells in the elderly or those with obesity is also associated with a dampened cellular repair and angiogenic response and a reduced expression of Sirtuin-1 (SIRT1), a positive regulator of anti-inflammatory response and AT beiging/browning." (PMID 35211733, 2022). "Interestingly, increased peripheral levels of SIRT1 were frequently reported to reduce the accumulation of fat and decrease the risk of obesity, hypertension, hyperlipidemia, and diabetes; the low expression of SIRT1 therefore predisposes to the development of MetS." (PMID 33324265, 2020). "Moreover, alpha-mangostin treated diet induced obesity mice experienced weight loss, improved glucose and lipid profile and reduced liver fat accumulation through a Peroxisome proliferator-activated receptor gamma and SIRT-1-AMPK pathway." (PMID 32962190, 2020). "Interestingly, the modulation of hypothalamic SIRT1 has been implicated in the reduction of leptin resistance as a strategy for treating obesity, and the activation of SIRT1 by resveratrol improves peripheral and central leptin signaling and reverses leptin resistance caused by diet-induced obesity." (PMID 33202604, 2020). "Taken together, the observed effect of vitamin D on muscle fat accumulation and mRNA levels involved in mitochondrial biogenesis and function with AMPK/SIRT1 activation may demonstrate the beneficial effect of vitamin D on obesity and its associated metabolic disorders." (PMID 31744213, 2019). "Our data indicate that AT SIRT1 may be important for obesity-associated insulin resistance." (PMID 29417372, 2018). "Since SIRT1 increases lipolysis and suppresses inflammatory responses, it is plausible that its decreased expression in the adipose tissue of obese individuals might be associated with excessive fat accumulation and development of obesity-related inflammation." (PMID 27104517, 2016). "Finally, I will explore how hypothalamic SIRT1 may be involved in age-associated weight gain and diet-induced obesity by regulating leptin and insulin sensitivity in the central nervous system." (PMID 26236282, 2015). "Interestingly, single nucleotide polymorphisms in SIRT1 are associated with obesity." (PMID 24374551, 2014). "The interesting novel results suggest that Akt2 and Sirt1 may be implicated in porcine obesity." (PMID 23951196, 2013). "Thus, targeting central Sirt1 signaling may show promise for the treatment of obesity and the associated disorders." (PMID 20020036, 2009). "SIRT1 was reduced in visceral versus subcutaneous AT and in patients with obesity with type 2 diabetes mellitus." (PMID 42256458, 2026). "Intervention targeting NAMPT has the potential to break the vicious cycle of SIRT1/NAMPT/NAD+/SIRT1 and reverse the clinical course of obesity induced OSA." (PMID 39901373, 2025). "RT-qPCR showed obesity reduces the mRNA level of Sirt1 gene in hippocampal tissue, whereas exercise increases it." (PMID 41140914, 2025).
Obesity (continued). "Previous observations suggest that RES activates SIRT1 in the biological tissue of individuals with obesity and HFD rodents, which in turn protects against HFD‐induced metabolic damage through preserved lipid and energy metabolism and reduced inflammation." (PMID 40349319, 2025). "It has been interpreted that resveratrol is effective against diet-induced obesity and insulin resistance and SIRT1 is a crucial regulator of energy and metabolic homeostasis." (PMID 40363789, 2025). "Both liraglutide and semaglutide have been shown to reduce obesity-induced muscle atrophy via a GLP-1/Sirtuin (SIRT1) pathway in rodents." (PMID 41367404, 2025). "Similar study emphasized the role of AMPK/SIRT1/PCG-1α pathway as a target of obesity treatment using other dietary products." (PMID 40050385, 2025). "Sirtuins, particularly sirtuin 1 (SIRT1), are associated with metabolic diseases such as obesity and diabetes." (PMID 39871746, 2025). "Concurrently, obesity suppresses SIRT1 expression and activity, impairing its deacetylation of downstream targets." (PMID 41268687, 2025). "According to some studies, the alternative alleles of rs12778366 and rs7895833 polymorphisms in the promoter region of the SIRT1 gene are associated with AMD, T2DM, obesity, glucose tolerance, hypertension development risk, and preeclampsia." (PMID 40243583, 2025). "In healthy men with obesity, 30 days supplementation at 150 mg per day enhanced SIRT1 and PGC-1α protein levels, activated AMPK, decreased circulating glucose and insulin levels, insulin resistance, IL-6, IL-8 and TNF-α concentrations." (PMID 40642166, 2025). "Western blot analysis showed exercise and obesity independently regulate the SIRT1/PGC1α pathway: exercise upregulates its expression, whereas obesity downregulates its expression." (PMID 41140914, 2025). "SIRT1 also enhances insulin sensitivity, stimulates lipid oxidation, and suppresses lipogenesis, offering benefits for managing obesity and type 2 diabetes." (PMID 41254699, 2025). "HIIT exercise, as the most effective exercise program to combat obesity in recent years, can also play a particularly important regulatory role in SIRT1." (PMID 41140914, 2025). "While this study establishes the DNMT3a/SIRT1 axis as a mechanistic pathway for RRTFB's anti‐obesity effects, several limitations should be acknowledged." (PMID 40909259, 2025). "It is noteworthy that hepatic Sirt1 expression increases during nutrient deprivation and decreases in obesity, particularly in peripheral tissues such as the liver of DIO mice, which are often affected by MASLD." (PMID 40806011, 2025). "Previous research has reported that Cel ameliorates mitochondrial function in obesity models via the AMPK/SIRT1 axis, and this work for the first time reveals a novel mechanism by which it regulates autophagy through the AMPK/ULK1 pathway in the context of AS." (PMID 41347171, 2025). "Studies have shown that mice overexpressing SIRT1 exhibit reduced obesity, with stronger effects in females than males, likely due to the ER-α-mediated induction of SIRT1." (PMID 41304967, 2025). "This demonstrates the complex role of SIRT1 in modulating link between obesity and breast cancer through hormone regulation." (PMID 41300302, 2025). "The observed downregulation of Sirt1 in DIO animals injected with shOlfr734 accords with the established regulation of this deacetylase in obesity." (PMID 40806011, 2025). "SIRT1 plays a key role in protection against CVDs, metabolic syndrome, obesity, vascular endothelial function, and ischemia-reperfusion damage." (PMID 41567643, 2025). "In mice with obesity-related renal disorders, SIRT1 overexpression reduced oxidative stress and cell aging-induced renal pathological damage." (PMID 41304967, 2025). "Prostaglandin E2 (PGE2), elevated in obesity, down-regulates SIRT1, leading to increased aromatase expression and estrogen production in adipose tissue." (PMID 41300302, 2025).